PBK (PDZ binding kinase)
Diseases named in the same sentence as PBK in open-access papers (continued):
Sharing a sentence is not in itself a finding about the gene and the disease.
prostate carcinoma (26 papers, 2015 to 2026). A carcinoma that arises from epithelial cells of the prostate gland. "PBK was reported to regulate the expression of androgen receptor (AR) protein, and the overexpression of PBK in aggressive prostate cancer was reported to be associated with early biochemical relapse and poor clinical manifestations." (PMID 35360870, 2022). "Based on WGCNA module selecting and gene expression analysis, BUB1, KIF2C, CDC20, and PBK were eventually detected to be potentially associated with the clinical pathological features of prostate cancer." (PMID 35360870, 2022). "Modulation of PBK expression and function causally regulates the invasive ability of prostate cancer cells." (PMID 25909225, 2015). "Using archival tissue samples, gain-of-function and loss-of-function studies, we show that PBK expression is up-regulated in prostate cancer, and its expression level is commensurate with invasiveness." (PMID 25909225, 2015). "As such, we demonstrated that PBK/TOPK levels causally regulate invasion in human prostate cancer cells in vitro." (PMID 25909225, 2015). "Additionally, we identified five downstream genes (IGF1R, BMI1, RHAMM, NuSAP1, and PBK) of E2F1 in prostate cancer, and these genes are associated with the survival and proliferation of prostate cancer." (PMID 38374143, 2024). "Moreover, PBK was a downstream target of RORγ that exerted the cellular effects, indicating that PBK, RORγ, and AR were all associated with the growth and survival of aggressive prostate cancer." (PMID 35360870, 2022). "In the patient cohort we analyzed, PBK/TOPK is associated with poorly differentiated prostate cancer, its nuclear localization is strongly correlated with metastatic prostate cancer, and β-catenin is important for mediating the aggressive outcome of PBK expression in vitro." (PMID 25909225, 2015). "Overexpression of PBK/TOPK in VCaP cells increased cell proliferation significantly, while the loss of PBK/TOPK in PC3M cells reduced cell proliferation more strongly, suggesting that PBK/TOPK levels are also associated with the proliferative potential of prostate cancer cells." (PMID 25909225, 2015). "Therefore, although PBK expression is strongly associated with higher-grade prostate cancer, we hypothesize that PBK's expression is driven by a factor other than the AR." (PMID 25909225, 2015). "Some studies also revealed that the expression levels of PBK and kinase activity are positively correlated with the G2/M phase cell numbers in prostate cancer and gastric carcinoma." (PMID 38215156, 2024). "PBK is highly expressed in a variety of tumors, including lung, colorectal, ovarian, and prostate cancers, and patients with tumors accompanied by high PBK expression often have a worse prognosis." (PMID 35906548, 2022). "Recently, several studies showed that PBK is overexpressed in multiple cancer types including prostate cancer." (PMID 33916325, 2021). "Of note, multiple genes hitherto known to be associated with prostate cancer progression were observed in the top list of upregulated entities including but not limited to MYBL2, ESM1, PBK, and UBE2C in PC3, and MMP1, CCL5, and STC1 in DU145." (PMID 31493351, 2019). "Given that androgen receptor (AR) signaling is a key driver of the tumor phenotype in both treatment-naïve and castration-resistant prostate cancer, we investigated if AR is able to regulate PBK expression." (PMID 25909225, 2015). "Our in vitro data have been consistent with a role for PBK/TOPK in facilitating invasion in prostate cancer." (PMID 25909225, 2015). "The clinical relevance of our study of the role of PBK/TOPK expression in prostate cancer was examined by analyzing a large patient cohort (n = 120)." (PMID 25909225, 2015). "The aim of this study was to evaluate the role of PDZ Domain-binding kinase (PBK) in prostate cancer and to determine if PBK expression enhances aggressiveness in prostate cancer." (PMID 25909225, 2015).
prostate carcinoma (continued). "We observed that total PBK/TOPK protein expression correlates well with the invasive ability of the prostate cancer cell lines." (PMID 25909225, 2015). "Together, these data indicate that PBK/TOPK causally regulates the migratory and invasive ability of prostate cancer cells." (PMID 25909225, 2015). "The pathway that we found most consistently and strongly activated in the presence of PBK/TOPK in multiple prostate cancer cell lines was that of β-catenin-TCF/LEF signaling." (PMID 25909225, 2015). "To determine if PBK/TOPK is associated with invasive prostate cancers, we began by examining PBK/TOPK expression in a panel of prostate cancer cell lines." (PMID 25909225, 2015). "Our results indicate that activation of β-catenin-TCF/LEF signaling is critical for PBK/TOPK-dependent prostate cancer cell invasion." (PMID 25909225, 2015). "In the present report, we show that ectopic expression of PBK/TOPK in less aggressive prostate cancer cells greatly increased their invasive ability." (PMID 25909225, 2015). "The observation that PBK/TOPK expression level is commensurate with the invasive properties of prostate cancer cells prompted us to examine if prostate cancer cells with low endogenous PBK/TOPK show increased invasiveness upon ectopic expression of PBK/TOPK." (PMID 25909225, 2015). "We wanted to examine if PBK/TOPK is differentially expressed in human prostate carcinoma, as compared to normal prostate, and the functional consequences of its expression." (PMID 25909225, 2015). "Importantly, PBK has been shown to be central for the invasive and migratory function of prostate cancer cells." (PMID 28978135, 2017). "It has recently been reported that PBK is present in primary prostate cancer; however, the molecular and phenotypic implications of its presence in aggressive prostate cancer remain speculative." (PMID 25909225, 2015). "Thus, we have been able to experimentally establish, for the first time, a direct role and a molecular mechanism for PBK/TOPK to facilitate aggressiveness in prostate cancer cells." (PMID 25909225, 2015). "Together, these data suggest that, similar to genetic knockdown, pharmacological inhibition of PBK strongly reduces two hallmarks of cancer in prostate cancer cells, namely, invasive ability, via down-regulation of β-catenin-mediated production of MMP-2 and -9, and proliferation." (PMID 25909225, 2015). "We corroborate our in vitro studies with a large cohort of human prostate cancer tissue samples and show a direct correlation of PBK/TOPK expression with poorly differentiated prostate cancers, and accumulation of the kinase in invasive primary tumors and particularly distant metastases." (PMID 25909225, 2015). "Additionally, we observed strong PBK/TOPK localization in human prostate cancer bone, lymph node and abdominal metastases." (PMID 25909225, 2015). "In addition, overexpression of PBK/TOPK may lead to high malignant phenotype prostate cancer (PCa), while knockdown of PBK/TOPK suppressed cell proliferation, invasion, and migration of PCa cell lines in vitro." (PMID 33670114, 2021). "Our in vitro and in situ data are in agreement that PBK could be a prognostic biomarker for prostate cancer that would discriminate aggressive prostate cancer from indolent disease, and is a potential target for the therapeutic intervention of aggressive prostate cancer in men." (PMID 25909225, 2015). "Notably, inhibition of β-catenin signaling reduced gelatinolytic activity of conditioned media and invasive ability of PBK-overexpressing VCaP cells to almost control levels, showing that β-catenin signaling mediates the upregulation of PBK/TOPK-dependent invasion in prostate cancer cells." (PMID 25909225, 2015). "We found that a very high percentage (59%) of prostate cancers with distant metastases express high levels of PBK/TOPK and ~30% of these cancers have predominantly nuclear localization of PBK/TOPK." (PMID 25909225, 2015).
prostate carcinoma (continued). "Normal (n = 4), benign prostate hyperplasia (n = 4) and prostate cancer (n = 8) samples were lysed and PBK/TOPK protein levels were determined using Western blot analyses." (PMID 25909225, 2015). "Most interestingly, metastatic lesions of prostate cancer in abdominal wall, lymph node and bone show robust PBK/TOPK levels and nuclear localization." (PMID 25909225, 2015). "The results showed that 7 genes were all associated with prostate cancer prognosis, but only UBE2C, TOP2A and CCNB1 were high expression in prostate cancer samples than normal prostate gland samples, the expression of PBK, CDKN3, AURKA, MKI67 were not." (PMID 33630978, 2021). "Together, our data provide strong evidence that PBK/TOPK is present in prostate cancer cells and not in normal non-tumorigenic cells and its level increases with distant metastasis and invasive ability." (PMID 25909225, 2015). "Tumor-adjacent normal tissues and prostate cancer sections with low Gleason score were frequently negative or possessed weak PBK/TOPK protein expression." (PMID 25909225, 2015). "UBE2C, PDZ-binding kinase (PBK), cyclin B1 (CCNB1), Cyclin-dependent kinase inhibitor 3 (CDKN3), topoisomerase II alpha (TOP2A), Aurora kinase A (AURKA) and MKI67 were identified as the candidate hub genes, which were all correlated with prostate cancer patient’ disease-free survival in TCGA." (PMID 33630978, 2021). "Together, we provide evidence that PBK/TOPK, by induction of a pro-metastatic gene expression program in prostate cancer cells, triggers aggressive behavior and we propose evaluation of PBK/TOPK as a prognostic marker and therapeutic target in men with aggressive prostate cancer." (PMID 25909225, 2015). "Interestingly, the two tissue samples that lacked PBK/TOPK were stage I and II prostate cancers while four of the six tissue samples with detectable PBK/TOPK levels were stage IV prostate cancer." (PMID 25909225, 2015).
ovarian carcinoma (25 papers, 2017 to 2026). A malignant neoplasm originating from the surface ovarian epithelium. "PBK/TOPK was also found to be significantly associated with the progression of human bladder cancer, nasopharyngeal carcinoma, and ovarian cancer." (PMID 33670114, 2021). "In epithelial ovarian cancer, high PBK expression is significantly associated with poor progression-free survival (PFS) and OS in early-stage cases." (PMID 30778048, 2019). "Considering that PBK expression was associated with lymph node metastasis in the patient cohort, we hypothesized that PBK participated in the metastasis of ovarian cancer cell lines." (PMID 30778048, 2019). "PBK promotes autophagy in ovarian cancer cells by phosphorylating ERK1/2 and thereby activating the mTOR pathway while increasing cisplatin resistance." (PMID 38460944, 2024). "The colony formation assay drew the same conclusion that PBK promotes olaparib resistance in ovarian cancer cells." (PMID 35859118, 2022). "Here, we reported that the abnormal expression of PBK renders ovarian cancer resistant to olaparib treatment dependent on TRIM37 mediated NFκB activation." (PMID 35859118, 2022). "The PBK/TRIM37/NFκB axis served as a crucial signaling pathway involved in the PARPi resistance of ovarian cancer." (PMID 35859118, 2022). "Altogether, using the PBK inhibitor in combination with olaparib possessed the potential to overcome PARPi resistance in ovarian cancer." (PMID 35859118, 2022). "Blocking the activity of PBK, either pharmacologically or genetically, enhanced the sensitivity of ovarian cancer cells to olaparib." (PMID 35859118, 2022). "In the current study, we demonstrated that overexpression of PBK contributed to olaparib resistance in ovarian cancer cells." (PMID 35859118, 2022). "PBK was over-expressed in olaparib-resistant ovarian cancer cells and knockdown of PBK increased the apoptotic cell death induced by olaparib." (PMID 35859118, 2022). "As such, the application of PBK inhibitor provided a potential strategy for sensitizing ovarian cancer to PARPi." (PMID 35859118, 2022). "Targeted inhibition of PBK using a specific inhibitor increased the sensitivity of ovarian cancer to olaparib." (PMID 35859118, 2022). "Recent study has suggested that overexpression of PBK decreased ovarian cancer responsiveness to cisplatin treatment through inducing autophagy in vivo." (PMID 34859049, 2021). "The results from datasets within Oncomine and GEPIA also showed that PBK was overexpressed in ovarian cancer samples compared with the peritoneum or ovarian surface epithelium tissues." (PMID 30778048, 2019). "Correspondingly, the overexpression of PBK conferred ovarian cancer cells with cisplatin resistance." (PMID 30778048, 2019). "Overexpression of PBK decreased ovarian cancer responsiveness to cisplatin treatment through inducing autophagy in vivo." (PMID 30778048, 2019). "Our results indicated the bright prospect of combining a PBK inhibitor with cisplatin for ovarian cancer therapy." (PMID 30778048, 2019). "Overexpression of PBK attenuated ovarian cancer cell sensitivity to cisplatin treatment and promoted autophagy flow through the ERK/mTOR axis." (PMID 30778048, 2019). "In this study, overexpression of PBK attenuated the sensitivity of ovarian cancer cells to cisplatin treatment through inducing autophagy in vitro and in vivo." (PMID 30778048, 2019). "We further found that NFκB activated by PBK/TRIM37 confers resistance to PARPi in ovarian cancer." (PMID 35859118, 2022). "In addition, PBK contributed to PARPi resistance of ovarian cancer through the TRIM37/NFκB axis in vitro and in vivo." (PMID 35859118, 2022). "Consistently, overexpression of PBK conferred ovarian cancer cells resistance to olaparib." (PMID 35859118, 2022). "Our findings indicated that PBK could confer ovarian cancer cells with cisplatin resistance in vivo." (PMID 30778048, 2019).
ovarian carcinoma (continued). "We next determined whether the overexpression of PBK could reverse cisplatin-induced cell death in ovarian cancer cells." (PMID 30778048, 2019). "The regulation of autophagy through modulating PBK might be an effective method for ovarian cancer treatment." (PMID 30778048, 2019). "Thus, the overexpression of PBK activated ovarian cancer cell autophagy through suppressing the mTOR signaling pathway." (PMID 30778048, 2019). "Here, we verified for the first time that PBK could promote ovarian cancer cell autophagic flux through activating the mTOR pathway." (PMID 30778048, 2019). "Furthermore, the expression levels of PBK in most ovarian cancer cell lines (5/6) were obviously higher than those in FTE187 cells." (PMID 30778048, 2019). "We speculated that these pathways might be involved in the PBK-induced chemoresistance and metastasis of ovarian cancer." (PMID 30778048, 2019). "However, the role of PBK in PARPi resistance of ovarian cancer is obscure." (PMID 35859118, 2022). "Therefore, PBK cooperated with TRIM37 to activate the NFκB signaling pathway in ovarian cancer." (PMID 35859118, 2022). "Thus, our data suggested that PBK confers olaparib resistance of ovarian cancer in vivo." (PMID 35859118, 2022). "Thus, we speculated that EVI1/PBK might be an important axis in promoting the progression of ovarian cancer malignant behavior." (PMID 30778048, 2019). "Thus, EVI1 could regulate PBK transcription through directly targeting the PBK promoter in ovarian cancer cells." (PMID 30778048, 2019). "Finally, we tried to determine the regulatory mechanism of PBK in ovarian cancers." (PMID 30778048, 2019). "Therefore, PBK is a promising molecular target for targeted therapy in ovarian cancer." (PMID 30778048, 2019). "Therefore, increased expression of PBK contributed to the cisplatin resistance of ovarian cancer." (PMID 30778048, 2019). "Eight genes (NUF2, GTSE1, DEPDC1, KIF18B, PBK, CEP55, HJURP, SKA1) were potential hub genes correlated to ovarian cancer progression." (PMID 35173547, 2022). "In conclusion, in this study, we demonstrated that PBK directly interacts with TRIM37 to promote its phosphorylation and nuclear translocation, which subsequently activates the NFκB pathway in ovarian cancer cells." (PMID 35859118, 2022). "However, the role of PBK in the PARPi resistance of ovarian cancer remains unclear." (PMID 35859118, 2022). "Here, our results also showed that PBK expression is strongly upregulated in HGSOC tissues and ovarian cancer cell lines." (PMID 30778048, 2019). "However, the functional mechanism of PBK in ovarian cancer remains unknown." (PMID 30778048, 2019). "However, the regulatory mechanism of PBK in ovarian cancer remains unclear." (PMID 30778048, 2019). "In summary, our study showed that PBK was highly expressed in HGSOC samples and ovarian cancer cell lines." (PMID 30778048, 2019). "PBK is called PDZ Binding Kinase, and studies have demonstrated that PBK is an effective drug target with multiple therapeutic potentials in a variety of cancers, such as ovarian cancer, prolactinoma, and cervical cancer." (PMID 38661103, 2024). "In conclusion, PBK confers ovarian cancer resistance to PARPi through activating the TRIM37-mediated NFκB pathway, and targeted inhibition of PBK provided the new therapy to improve PARPi treatment outcomes for ovarian cancer patients." (PMID 35859118, 2022). "Considering that PBK was involved in the regulation of the MAPK and PI3K–AKT signaling pathway, which mediates the progression of autophagy, we investigated the role of PBK in the autophagy of ovarian cancer cells." (PMID 30778048, 2019). "OTS514 failed to inhibit ovarian cancer cell proliferation in PBK-knockdown cells, suggesting that OTS514 exerted a growth-inhibitory effect dependent on PBK expression." (PMID 30778048, 2019). "Until now, there is no report about the function of PBK in ERK1/2 phosphorylation in ovarian cancer." (PMID 30778048, 2019).
ovarian carcinoma (continued). "The combination of a PBK inhibitor with traditional chemotherapy drugs might be a novel approach for ovarian cancer therapy." (PMID 30778048, 2019). "Additionally, the overexpression of PBK failed to promote ovarian cancer cell autophagy with mTOR or ERK1/2 knockdown, and the restoration of mTOR or ERK1/2 expression could partly rescue the autophagy blocked by knockdown of mTOR or ERK1/2 in A2780 and SKOV3 cells." (PMID 30778048, 2019).